TNF (tumor necrosis factor)
Diseases named in the same sentence as TNF in open-access papers (continued):
Sharing a sentence is not in itself a finding about the gene and the disease.
autoimmune disease (continued). "While there are several approved TNFα inhibitors used to treat autoimmune diseases, a significant subset of patients is nonresponsive to TNFα inhibitors or becomes resistant to treatment." (PMID 33776573, 2021). "This is supported by evidence that antibodies to TNFα exist to some extent even in healthy subjects and in individuals with autoimmune disease, while a similar literature does not exist for antibodies to TL1A." (PMID 34970265, 2021). "We conclude that WJ-MSCs primed by TNF-α and IFN-γ may represent a promising tool to treat the autoimmune disorders and can provide a new evidence to consider MSCs- based therapeutic approach for the treatment of TID." (PMID 34650558, 2021). "Fish tumor necrosis factor (TNF) family members are cytokines with multiple effects, which play vital roles in cell growth, differentiation, proliferation and immunity, apoptosis, macrophage activity and autoimmune diseases." (PMID 34869718, 2021). "Since GCs are observed in the lesions of autoimmune diseases and lymphomas, targeting the MMP3/TNFα-mediated migration of stromal cells in the B cell follicle may have great potential as a future therapeutic modality against aberrant GC-associated disorders." (PMID 34222497, 2021). "Unlike immunosuppressive biologic therapies [tumor necrosis factor (TNF)-alpha inhibitors] used for the treatment of autoimmune disease, very few investigational protocols incorporating anti-PD-1 or anti-PD-L1 therapy require TB screening." (PMID 34233733, 2021). "Th 1 cytokines, such as TNF-α and IFN-γ, are known to lead the progression of autoimmune diseases such as type 1 diabetes and multiple sclerosis (MS), while IL-4, IL-10, and IL-13 refer to Th 2 cytokines and inhibit the pro-inflammatory response and reduce damage." (PMID 34445510, 2021). "Although there are numerous studies on TNF-α in various autoimmune diseases, the pathological mechanism and research progress with respect to the role of TNF-α in uveitis have not been reviewed." (PMID 34795583, 2021). "Anti-TNF therapies used clinically for immune/autoimmune diseases have failed the clinical trial to manage body weight in obese people, suggesting that targeting TNF alone is not effective." (PMID 33076522, 2020). "Due to the crucial roles of IL-17 and TNF-α in autoimmune diseases and the contribution of NDR1 in IL-17 signaling, NDR1 could be a potential target for drug discovery of autoimmune diseases like EAE, RA, IBD, MS, and UC." (PMID 32265942, 2020). "Although the anti-TNF agents infliximab and adalimumab have revolutionized the treatment of autoimmune diseases, a significant percentage of patients do not respond to this therapy." (PMID 32397546, 2020). "This indirectly suggests that enhanced AMPK signaling would not counteract stimulation of TNF-α-NF-κB signaling in autoimmune diseases." (PMID 32059381, 2020). "At least, IL-2, IL-6, TNF-α, IFN-γ were produced when co-cultures of CII-CAR-T cells and fresh cartilage, and these cytokines also play roles in the occurrence and development of inflammatory arthritis and other autoimmune diseases." (PMID 33343563, 2020). "The variant TNF-α gene promotor, which is not bound nor repressed by LRRFIP1/GCF2 is discussed in relation to autoimmune diseases in Section 3.1." (PMID 30709060, 2019). "RA is an autoimmune disease in which osteochondral destruction occurs with the increased expression of RANKL and MMPs from synovial tissues by excessive inflammatory cytokines such as TNF-α and IL-6." (PMID 31698687, 2019). "Moreover, understanding the precise effect of TNFα/TNFR2 on the development and function of iTreg will promote iTreg therapy for patients with autoimmune diseases in the future." (PMID 30631042, 2019).
autoimmune disease (continued). "It has been reported that α-GalCer stimulation can induce iNKT cells to produce both anti-inflammatory cytokines (e.g., IL4, IL13, and IL10) and pro-inflammatory cytokines (e.g., IFNγ, TNFα, and IL17), ultimately determining the outcome of autoimmune diseases such as EAE." (PMID 30766446, 2019). "TNF-α plays multiple roles in the development and function of the immune system and manipulation of TNF-α and its receptors and has revealed numerous aspects of their functions in autoimmune disease, such as T1D." (PMID 31049023, 2019). "Similarly, IRAK4 inhibitors, ND-2158 and ND-2110 attenuated TNFα production from TLR4/9-stimulated human PBMCs and autoimmune disease in collagen-induced arthritis and gout murine models." (PMID 31354711, 2019). "Tumour necrosis factor (TNF) signalling is mediated via two receptors, TNF-receptor 1 (TNFR1) and TNF-receptor 2 (TNFR2), which work antithetically to balance CNS immune responses involved in autoimmune diseases such as multiple sclerosis." (PMID 30206422, 2018). "Furthermore, CS significantly reduces the cytotoxic activity of natural killer (NK) cells, which destroy auto-reactive T cells that promote autoimmune disease, and reduces the production of IFN-γ and TNF-α by activated NK cells." (PMID 29598831, 2018). "Indeed, mTNF alone may be enough to form TNF-dependent secondary lymphoid organ structure and granulomas, and to partially provide resistance to pathogens, without causing any autoimmune diseases." (PMID 29725328, 2018). "Interestingly, TNF-α, IL-12p70, IFN-γ and IL-2 belong to the cytokines T Helper 1 (Th1) that mediate the development of organ-specific autoimmune disease and are considered as positive effectors of inflammation." (PMID 30018377, 2018). "Anti-TNF-α treatments are not effective in some of the autoimmune diseases in which TNF-α is involved." (PMID 29541073, 2018). "In contrast to the pro-inflammatory effects of TNF/TNFR1 signaling, TNF/TNFR2 signaling preferentially activates, stabilizes, and expands Tregs to mediate their immunosuppressive effects and contribute to the treatment of autoimmune disease." (PMID 30079066, 2018). "These compounds present low toxicity and may be further optimized in drug design targeting TNF and RANKL to develop improved treatments for a range of inflammatory and autoimmune diseases." (PMID 28426652, 2017). "Similarly, in our study, we found that TSG-6 was able to downregulate IFN-α and TNF-α production in CpG-A or R847 stimulated human pDCs, making TSG-6 a potential immunomodulator for autoimmune disorders such as SLE." (PMID 28367002, 2017). "TNF-α genes are situated in the region of HLA class III (250-kb centromeric of the HLA-B and 850-kb telomeric of the class II HLA-DR genes in humans) and were found to be involved in the incidence and progression of some contagious and autoimmune diseases." (PMID 28119492, 2017). "Although the treatment of autoimmune diseases has improved due to the development of so-called biologics, like tumor necrosis factor alpha (TNFα) inhibitors, a large proportion of patients are still not adequately responding to these treatments." (PMID 28163705, 2016). "Anti-TNF-α therapy is clinically effective in the management of autoimmune diseases; however, the mechanisms by which anti-TNF-α therapy exerts a clinical effect are currently not fully understood." (PMID 26834751, 2016). "A study on the effect of vitamin D on monocyte expression of TNF-α showed that 1,25(OH)2D3 could significantly suppress TNF-α, which plays an important role in the pathogenesis of autoimmune diseases." (PMID 25654127, 2015). "Our results support the inhibtory role of tolDCs in autoimmune diseases, although the bone marrow DCs in our study were isolated in the absence of LPS and TNF-α." (PMID 26107250, 2015).
autoimmune disease (continued). "Although different autoimmune disorders share TNF-α as a major player in disease pathology, there are likely to be alterations in TNF-α regulation that can distinguish between different disease manifestations and respond to different types of TNF-α blocking strategies." (PMID 24783218, 2014). "Tumor necrosis factor (TNF) related to apoptosis-inducing ligand (TRAIL/Apo2L/TNFSF10) is a member of the TNF super family of proteins involved in cancer development and autoimmune diseases, and is expressed in human and rodent testis, including germ cells, Sertoli cells, and Leydig cells." (PMID 24736722, 2014). "The effect of marine-derived n-3 PUFAs supplementation on CRP, IL-6 and TNF-α in subjects with chronic no-autoimmune disease (data were log-transformed before analysis)." (PMID 24505395, 2014). "For the autoimmune diseases above, either IL-33 or ST2 expression was altered in the serum of active patients, and this may be correlated with inflammatory cytokines, such as TNF-alpha and IL-1beta." (PMID 24151520, 2013). "Further randomized controlled studies on the relationship between TNF-α inhibitors and glycemic control are warranted, along with more studies examining the possible therapeutic role of TNF-α inhibitors in controlling other autoimmune diseases, such as DM." (PMID 22234148, 2012). "In this study, we show that in the MRL/lpr autoimmune disease model, levels of IFN-γ and TNF-α are augmented in the taste epithelium, which is accompanied by increased infiltration of T lymphocytes, suggesting the presence of chronic inflammation in the taste tissue." (PMID 22536412, 2012). "By multivariable analyses, IL-8 and TNFα, but not MIF levels, were associated with the diagnosis of an underlying autoimmune disease." (PMID 20596538, 2010). "Here, we will review some of our studies that focused on dissecting the precise mechanism of how TNFα, interferon-inducible protein of 10kDa (IP-10, CXCL10) or general virus infections can induce, accelerate or abrogate autoimmune disease in an animal model for T1D." (PMID 23675028, 2007). "TNF-α antagonists such as HUMIRA (Adalimumab) and Enbrel (Etanercept) neutralize TNF-α signaling to inhibit excessive macrophage apoptosis, an effect that has been validated in autoimmune disease models, demonstrating the alleviation of tissue inflammation and the maintenance of immune homeostasis." (PMID 40486507, 2025). "These targeted therapies, including anti-TNF, anti-IL-6, and anti-CD20 agents, are essential in autoimmune disease management and may provide disease stabilization without significant risk of autoimmune disease activation." (PMID 40461909, 2025). "B cells are important effector cells that are involved in the pathogenesis of autoimmune diseases through the production of auto-antibodies, the promotion of CD4+ T cell responses via antigen presentation, and the release of inflammatory cytokines (e.g., TNF-α and IL-6)." (PMID 38339108, 2024). "Lastly, TNF-α both promotes and inhibits inflammation through signaling through TNFR1 and TNFR2, and the differential signaling through these receptors on various types of cells, including Th1 and Th17 cells, can lead to the pathogenesis of various autoimmune diseases." (PMID 39403935, 2024). "Further, systemic anti-TNFα therapy at dosages and modalities approved for autoimmune disorders may not be efficacious to prevent cochlear damage." (PMID 36902722, 2023). "Such a novel concept of the dual role of TNF could partially explain the paradoxical, although rare, negative effect of TNF inhibitors in some patients with autoimmune diseases." (PMID 36009588, 2022). "Interestingly, high levels of TNF-α and TNFR are found in autoimmune diseases." (PMID 34434197, 2021). "In 1997, a study confirmed that TNF-α is not essential for inducing experimental autoimmune diseases, and a chronic low level of TNF-α might exert protective effects." (PMID 34795583, 2021).
autoimmune disease (continued). "Analysis of IL-2, IFN-γ and TNF-α showed that the proportion of MAIT cells producing these cytokines was reduced in women with long-term type 1 diabetes compared with healthy donors regardless of autoimmune disease status." (PMID 34350463, 2021). "Notably for AIH and PBC but not for PSC, these include CTLA-4 and TNF-α genes which are identified in similar studies of wide ranging autoimmune disorders." (PMID 32793226, 2020). "In addition, TNF-α showed significant negative correlations with age at onset of autoimmune disease and with HDL cholesterol levels." (PMID 33202729, 2020). "A combination of AMPs with other non-aggressive biomarkers (e.g., TNF-α) could improve the diagnosis of autoimmune disorders in the early stage." (PMID 32457759, 2020). "A previous study on genetically engineered mice without secreted TNF but with regulated memTNF expression has shown that memTNF exhibits suboptimal pro-inflammatory function in vivo and is inferior to secreted TNF in driving autoimmune diseases." (PMID 31645676, 2020). "This study suggests that targeting of tmTNF–TNFR2 interaction may represent a novel strategy in the treatment of autoimmune diseases, especially in those patients that do not to respond to conventional anti-TNF treatment, by mobilization of TNFR2+ Tregs." (PMID 29632537, 2018). "Anti-TNF therapy may be helpful for the treatment of autoimmune diseases, without enhancing the plasma viremia in patients whose HIV disease is under control by cART." (PMID 28358311, 2017). "Taken together with previous studies by others, current biologic agents including IL-6 blockade and TNF inhibitors, highly efficacious in treating autoimmune diseases, may not work well for treating ALS." (PMID 27070121, 2016). "Specific inhibition of the cytokine, tumor necrosis factor-α (TNF), has revolutionized the treatment of patients with several autoimmune diseases, and genetically engineered anti-TNF antibody constructs now constitute a heavy medicinal expenditure in many countries." (PMID 25904915, 2015). "Such an understanding could drive the development of novel therapeutics which could be used to suppress the detrimental effects of TNF-α in autoimmune diseases without interfering with the essential host defense mechanisms that keep M. tuberculosis in check." (PMID 25999670, 2015). "It seems that, in some autoimmune disorders, the negative TNF/IFN cross-regulation loop is missed, leading to high serum levels of both cytokines in patients in which they may exert a pathological effect." (PMID 24465874, 2014). "In both systemic onset juvenile idiopathic arthritis patients and in Sjogren’s syndrome, TNF inhibition led to an increased IFN signature supporting the hypothesis that TNF- and IFN-driven pathologies may lie at opposite poles of the autoimmune disease spectrum." (PMID 25405351, 2014). "Additionally, the specificity of C-reactive protein and inflammatory cytokines (e.g. tumor necrosis factor-α and interleukin-6) for OSAS seems to be low because of the high basal levels of these substances in patients with inflammatory disease, autoimmune disease, and many other diseases." (PMID 23805411, 2013). "The development of the first anti-TNF medications, including soluble TNFR2 fusion proteins like Enbrel, were therapeutic for some patients with rheumatoid arthritis but consistently worsened or induced new autoimmune diseases like type 1 diabetes, lupus, or multiple sclerosis." (PMID 24391650, 2013). "Pro-inflammatory cytokines, such as TNF or IL12A, the T-cell activation molecule CD28, the regulatory molecules IL10, TGFB1 or the adhesion molecules ITGA4 and ITGB1 have all been evaluated previously as therapeutic targets for autoimmune diseases, including MS." (PMID 18030350, 2007).
autoimmune disease (continued). "However, a negative correlation with the same anatomical region has been reported in other populations with autoimmune diseases without anti-TNF treatment; then, the use of biological treatments could influence the behavior of DKK-1." (PMID 40981186, 2025). "Even this negative evidence, women with autoimmune disease may benefits from anti-TNF therapies." (PMID 35185598, 2021). "Since tmTNF is sufficient to promote important immune functions like self-tolerance and resistance to infection, selective neutralization of sTNF may be a superior therapeutic strategy to treat chronic inflammatory and autoimmune diseases compared to non-selective blocking of TNF." (PMID 32528961, 2020). "However, only five studies on anti-TNF agents were included in this meta-analysis and, among these, only two were performed in patients with autoimmune diseases, in which a clinical evaluation was done without a determination of the biological effects of anti-TNF agents on IGRA outcome." (PMID 29777119, 2018). "Thus, unlike autoimmune diseases such as RA, IL-6 and TNF-α may not be ideal therapeutic targets of ALS and the elevation of these two cytokines may be due to a secondary event of neuroinflammation rather than a cause of disease." (PMID 27070121, 2016). "However, while TNF expression and serum release is upregulated during inflammation data from animal experiments suggest that TWEAK is stably expressed in multiple tissues and downregulated on mRNA level in different disease models of sepsis and autoimmune diseases." (PMID 27124414, 2016). "Therefore, in the patients whose HIV disease is under control of HAART, the anti-TNF therapy may be helpful for the treatment of autoimmune disease without enhancing plasma viremia." (PMID 24453421, 2013). "Moreover, carriage of the TNFA -308A allele, related to higher TNF-α production, was previously reported to be associated with non-response to anti-TNF-α in patients with different autoimmune diseases among which RA." (PMID 21385363, 2011). "Third, while we attempted to minimize confounding by excluding patients with active infections, autoimmune diseases, or other cancers, we did not specifically control for Helicobacter pylori infection status or other potential sources of chronic inflammation that might influence TNF-α." (PMID 40299527, 2025). "We concluded that BTN-Kat is a convenient tool for studying the dynamics of TNF expression without interfering with its biological functions, while ITN-Kat is a prototype theranostic agent for TNF-dependent autoimmune diseases." (PMID 31544893, 2018). "The effect of marine-derived n-3 PUFAs from dietary intake on CRP, IL-6 and TNF-α was only assessed in subjects with chronic non-autoimmune disease, and significant lowering effect was only observed on IL-6, but not on CRP and TNF-α." (PMID 24505395, 2014). "The effect of marine-derived n-3 PUFAs from dietary intake was only assessed in subjects with chronic non-autoimmune disease, and a significant lowering effect was observed on IL-6, but not on CRP and TNF-α." (PMID 24505395, 2014). "Like FasL, TNF has also been involved in AICD, although unlike CD95, TNF initiates and exacerbates autoimmune diseases." (PMID 20799941, 2010). "Elevated IL-6 and TNF-α levels are not exclusive to GDM and may also be observed in other conditions, such as infections and autoimmune diseases, and also pregnancy-related conditions such as preeclampsia and preterm birth." (PMID 40722699, 2025). "Although BCG and CFA release TNF and therefore are not specific for TNFR2, they have low toxicity and thereby may be safe for treating autoimmune disease by virtue of inducing low levels of TNF." (PMID 24391650, 2013).
autoimmune disease (continued). "The synergistic action of IL-17 with TNF-α has been shown to have major pro-coagulant and pro-thrombotic effects, and furthermore, combined blockade of TNF-α and IL-17 has been shown to be a safe treatment strategy in autoimmune diseases where monotherapy is not fully effective." (PMID 34575667, 2021).